NKTR (natural killer cell triggering receptor)
Description:
PPIase that catalyzes the cis-trans isomerization of proline imidic peptide bonds in oligopeptides and may therefore assist protein folding. Component of a putative tumor-recognition complex involved in the function of NK cells.
Synonyms: p104; CypNK
Tractability: Antibody: UniProt places it where antibodies can reach, with high confidence; its Gene Ontology location is reachable by antibodies, with medium confidence. PROTAC: UniProt records ubiquitination sites on it; ubiquitination databases record sites on it; its protein half-life has been measured.
Gene: Protein-coding gene on chromosome 3 (42,600,471 to 42,648,738, forward strand). Ensembl gene ENSG00000114857.
Subcellular location: Cell membrane
Subcellular location (Human Protein Atlas): Cytosol; Nucleoplasm; Plasma membrane
Gene Ontology:
Molecular function: peptidyl-prolyl cis-trans isomerase activity; cyclosporin A binding
Biological process: protein folding
Cellular component: cytosol; nucleoplasm; plasma membrane; nucleus; nuclear lumen
Genetic constraint (gnomAD): Loss-of-function variants: 52 observed, 125.96 expected, observed/expected ratio (o/e) 0.41, 90% interval 0.33 to 0.52. The upper end of that interval is the gene's LOEUF score, 0.52, which puts it in group 2 of 6, group 1 being the genes least tolerant of losing a copy. Missense variants: 1,483 observed, 1,630.2 expected, observed/expected ratio (o/e) 0.91, 90% interval 0.87 to 0.95. Synonymous variants: 590 observed, 574.69 expected, observed/expected ratio (o/e) 1.03, 90% interval 0.96 to 1.1.
Homologues: Orthologues: chimpanzee NKTR (99% identical), macaque NKTR (96% identical), dog NKTR (90% identical), pig NKTR (89% identical), rabbit NKTR (84% identical), guinea pig NKTR (80% identical), mouse Nktr (79% identical), rat Nktr (78% identical), tropical clawed frog nktr (49% identical), zebrafish nktr (41% identical), Caenorhabditis elegans cyn-9 (8% identical), Drosophila melanogaster Cyp40 (7% identical). Paralogues in human: PPIG (20% identical), CWC27 (10% identical), PPIL4 (8% identical), PPID (8% identical), PPIL2 (6% identical), PPIC (6% identical), PPIB (6% identical), PPIE (6% identical), PPIH (6% identical), PPIA (6% identical), PPIF (6% identical), PPWD1 (6% identical), and 10 more.
Diseases named in the same sentence as NKTR in open-access papers:
NKTR is named in the same sentence as 26 diseases in open-access papers, as found by Europe PMC text mining. Sharing a sentence is not in itself a finding about the gene and the disease. The quoted sentences say what the papers report.
melanoma (4 papers, 2020 to 2022). A malignant, usually aggressive tumor composed of atypical, neoplastic melanocytes. "NKTR-214 has been shown to improve antitumor immunity in mouse cancer models, including the B16-F10 melanoma and the CT26 colon carcinoma when combined with the gp100 self TAA or the endogenous retroviral AH-1 TAA vaccine, respectively." (PMID 35651800, 2022). "Functional assay using the melanoma mouse model and the human melanoma tissues revealed that NKTR-214 expands, maintaining effector CD8+ T cells and depleting Tregs by effector CD8+ T cell-derived IFN-γ and TNF-α." (PMID 35432377, 2022). "In contrast, NKTR-214-induced intratumoral Treg depletion was observed across different tumor models in two different strains of mice, with similar trends also observed in tumors from patients with melanoma and renal cell cancer treated with NKTR-214." (PMID 32005826, 2020). "NKTR-214 administration increased the levels of both IFN-γ and TNF-α in B16.F10 tumor tissue and in human melanoma and RCC tumors." (PMID 32005826, 2020). "Although treatment with only the vaccine or NKTR-214 did not support antitumor immunity to B16-F10 melanoma, the combination delayed tumor growth." (PMID 35651800, 2022).
breast carcinoma (2 papers, 2015 to 2020). "Collectively, these results suggest that CDYL2a promotes breast cancer cell proliferation through, at least partly, regulating the alternative splicing of FIP1L1, NKTR, and ADD3 genes." (PMID 32373210, 2020).
depression (2 papers, 2020). "NKTR is also increased in expression in our previous blood biomarker studies of suicide in both males and females, as well as increased in expression in postmortem brain studies in depression and in schizophrenia, possibly underlying the effect of stress in those disorders." (PMID 30862937, 2020).
pancreatic cancer (2 papers, 2018 to 2024). "Rastelli L, Gupta S, Dahiya A, Jagga Z, Nandabalan K, Upmanyu S. Efficacy and immune modulation by BXCL701 a dipeptidyl peptidase inhibitor, NKTR-214 a CD122-biased immune agonist with PD1 blockade in murine pancreatic tumors." (PMID 30400835, 2018). "In a mouse model of pancreatic cancer, the triple therapy of BXCL701, NKTR-214, and PD-1 inhibitor achieved tumor regression in all mice." (PMID 38672409, 2024). "Our hypothesis was confirmed with the observation that BXCL701, in combination with an anti-PD-1 antibody and NKTR-214 (a CD122-biased agonist) results in complete and durable response with functional demonstration of immunologic memory in a syngeneic mouse model of pancreatic cancer (Pan02)." (PMID 30400835, 2018).
acute myeloid leukemia (1 paper, 2022). Acute myeloid leukemia (AML) is a group of neoplasms arising from precursor cells committed to the myeloid cell-line differentiation. "For the LIOTs, despite low indel frequency (below 3%), significantly detectable indels were found in the exon of nine cancer genes, such as U2AF2 and NKTR causing Acute myeloid leukemia (AML)." (PMID 35831290, 2022).
Alzheimer disease (1 paper, 2023). A progressive, neurodegenerative disease characterized by loss of function and death of nerve cells in several areas of the brain leading to loss of cognitive function such as memory and language. "In a recent study, researchers have identified and chosen three cerebrospinal fluid (CSF) markers, TNFRSF1B, CXCL10, and SPP1, along with three blood markers associated with Alzheimer’s disease (AD), which are GSTM3, TGFB1, and NKTR." (PMID 38259635, 2023).
brain tumor (1 paper, 2015). "The elevated and sustained SN38 concentrations in tumor compared to plasma after NKTR-102 administration indicates the retention of NKTR-102 within brain tumors serves as a reservoir for continued release of SN38 in the brain tumor microenvironment." (PMID 26463521, 2015). "The ability of NKTR-102 to cross the BTB and accumulate in brain tumor tissue appeared to contribute to the efficacy observed in this experimental model of BMBC." (PMID 26463521, 2015).
COVID-19 (1 paper, 2021). A disease caused by infection with severe acute respiratory syndrome coronavirus 2. "Several AD markers (CXCL10, TNFRSF1B, SPP1, TGFB1, GSTM3, and NKTR) have significantly altered expression in COVID-19 patients." (PMID 34108016, 2021). "NKTR and its PPI partners transcription initiation factor TFIID subunit 1 (TAF1), 40S ribosomal protein S14 (RPS14), and arrestin beta 2 (ARRB2) are differentially expressed in the PBMCs of COVID-19 patients." (PMID 34108016, 2021). "We identified several AD marker genes (e.g., NKTR, GSTM3, TGFB1, TNFRSF1B, SPP1, and CXCL10) which may provide insights into the shared pathobiology of cognitive dysfunction in COVID-19 and AD." (PMID 34108016, 2021).
myeloma (1 paper, 2020). "NKTR is required for natural killer-like activity in human T cells 50 and is supposed to be involved in tumor growth inhibition in a SP2/0 myeloma model." (PMID 32373210, 2020).
osteosarcoma (1 paper, 2021). A usually aggressive malignant bone-forming mesenchymal neoplasm, predominantly affecting adolescents and young adults. "Here, the authors investigated the efficacy of bempegaldesleukin (BEMPEG; NKTR‐214), a novel CD122‐preferential interleukin‐2 pathway agonist, in murine models of osteosarcoma." (PMID 33152115, 2021). "Therefore, we evaluated the efficacy of bempegaldesleukin (BEMPEG; NKTR‐214), a first‐in‐class CD122‐preferential IL‐2 pathway agonist, alone and in combination with anti‐PD‐1 or anti‐CTLA‐4 immune checkpoint inhibitors in metastatic and orthotopic murine models of osteosarcoma." (PMID 33152115, 2021).
renal cell carcinoma (1 paper, 2020). "In patients with metastatic melanoma and renal cell cancer, including those who had failed PD-1 CPI therapy, NKTR-214 monotherapy enhanced peripheral and intratumoral CD8+ T-cell proliferation and numbers without increasing intratumoral Tregs, and without causing serious toxicity." (PMID 32005826, 2020).
vitiligo (1 paper, 2022). Generalized well circumscribed patches of leukoderma that are generally distributed over symmetric body locations and is due to autoimmune destruction of melanocytes. "In addition, NK cells receptors, including natural killer cell triggering receptor (NKTR), killer cell lectin-like receptor C1 (KLRC1), CCL20, and NK cell-related cytokines such as TNFα and IL-15, are also increased in perilesional skin in patients with vitiligo." (PMID 35884944, 2022).
tumor (24 papers, 2015 to 2025). "We show that the combined therapy including NKTR-214 was able to control the growth of large, poorly immunogenic tumors and was associated with substantially higher expansion, tumor targeting and persistence of polyfunctional anti-tumor CD8 effector T cells." (PMID 32005809, 2020). "In the SP2/0 myeloma mice model infected with T. spiralis, genes encoding RpL41, NKTR, Rbbp4, and ANXA2 were enriched in tumor cells, suggesting a potential role in tumor growth inhibition." (PMID 40402283, 2025). "It is found that compared to ACT + IL-2, cells treated with ACT + NKTR-214 in vivo show increased polyfunctionality in spleen and tumor by 1.7-fold and 10-fold, respectively." (PMID 34000441, 2021). "A combination of vaccination and NKTR-214 markedly suppressed tumor growth and prolonged mouse survival for up to 2 months." (PMID 32005826, 2020). "Mice receiving ACT + NKTR-214 showed a median tumor growth delay (evaluated as time to reach a tumor volume of 1000 mm3) of 42 days compared to ACT + IL-2 or ACT + vehicle (19.5 and 11 days, respectively)." (PMID 32005809, 2020). "To test this principle, we used the pre-clinical pmel-1 mouse model to study the behavior of tumor-specific CD8 T cell expansion when NKTR-214 is combined with ACT compared to ACT + IL-2." (PMID 32005809, 2020). "In contrast, NKTR-214 therapy sharply reduced Treg levels in tumor tissue from the mice, as well as in tumors from patients." (PMID 32005826, 2020). "Here, we report that NKTR-214 promotes tumor regression in a variety of animal models of CPI therapy and vaccination." (PMID 32005826, 2020). "Hierarchical clustering of the most variable genes demonstrated that ACT + NKTR-214 induced far greater gene expression in tumor samples than ACT + IL-2 treatment." (PMID 32005809, 2020). "The expression of PD-1 was low or absent in the spleen of both treatments, while NKTR-214 enhanced activation of T cells in tumor in the mice treated with ACT + NKTR-214." (PMID 32005809, 2020). "At day 14, IL-2 preferentially expanded NK, while NKTR-214 expanded dramatically the T cell compartment, suggesting that the T cells are the main contributors in the enhanced anti-tumor response by NKTR-214 in this model." (PMID 32005809, 2020). "Vaccination and NKTR-214 treatment reduced both natural (neuropilinhi) and inducible (neuropilinlo) Tregs in tumor, with both Treg subsets restored upon cytokine neutralization." (PMID 32005826, 2020). "Together, these results demonstrate that NKTR-214 potentiates antitumor T cells and tumor regression after anti-PD-1 CPI therapy." (PMID 32005826, 2020). "ACT + NKTR-214 led to significant tumor growth inhibition with less frequent dosing in the aggressive B16-F10 model compared to ACT + IL-2 or ACT + vehicle." (PMID 32005809, 2020). "As a consequence, treatment with NKTR-214 resulted in preferential activation of T and NK cells with limited activation of Treg within the tumor microenvironment and provided anti-tumor efficacy across several syngeneic models." (PMID 31340613, 2019). "An increase in infiltrating cytotoxic CD8 T and NK cells to the tumor with complementary induction of dendritic cells, neutrophils and interferon-gamma-induced chemokines was observed in tumors after rucaparib+NKTR-214." (PMID 30400835, 2018). "NKTR-262 promotes an immune stimulatory environment and local injection site tumor antigen production limiting agonist release to systemic circulation." (PMID 30400835, 2018). "NKTR-262 treatment significantly increased clonality and infiltration of NKTR-214 expanded T cells, accelerating expansion of tumor infiltrating clones." (PMID 30400835, 2018). "NKTR-262 and NKTR-214 in combination showed efficacy in all tested tumor models, from significant tumor growth inhibition to complete tumor clearance in multiple models." (PMID 30400835, 2018). "Combining NKTR-262 with NKTR-214 engages the entire immune activation cascade required for systemic tumor clearance." (PMID 30400835, 2018).
tumor (continued). "NKTR-214 (IL-2Rβγ-biased cytokine) monotherapy stimulates proliferation and activation of lymphocytes in blood and tumor and increases PD-1/PD-L1 expression." (PMID 30400822, 2018). "NKTR-214 is a robust agonist of the IL-2 pathway and together with nivolumab promotes immune activation in the periphery and tumor microenvironment for significant clinical activity." (PMID 30400822, 2018). "NKTR-214 was invented to harness the potent immune stimulatory benefits of the IL2 pathway to maximize anti-tumor responses and minimize unwanted biological side effects." (PMID 28678791, 2017). "Overall, the data and mechanistic modeling suggest that the marked anti-tumor activity of NKTR-214 arises from the combination of sustained exposure and receptor bias, both of which are built into the molecular design of the agent." (PMID 28678791, 2017). "The receptor biased component of the NKTR-214 mechanism of action likely relates to the anti-tumor efficacy of the molecule by focusing its activity on CD8 and NK cells in the tumor microenvironment." (PMID 28678791, 2017). "NKTR-255, a polymer-conjugated recombinant human interleukin-15 agonist, significantly stimulated NK cell proliferation and expansion and further enhanced the in vitro cytotoxic activity and in vivo anti-tumor efficacy of anti-MCAM-CAR-NK cells against NB." (PMID 39554906, 2024). "Also enriched in this cluster was the natural killer triggering receptor NKTR, associated with IL-2 activation, and AAK1, implicated in chemokine receptor expression and trafficking to the tumor microenvironment." (PMID 38566989, 2024). "NKTR-214 is designed to sustain growth and survival of specific cancer-killing T cells and NK ells that specifically recognize a tumor target by targeting tumor infiltrating cells lymphocytes by binding to the CD122 receptor expressed by effector CD8+ T cells and NK cells." (PMID 35757002, 2022). "Interestingly, NKTR-214 preferentially expanded Thy1.1+ tumor-specific CD8 T cells over the endogenous Thy1.2+ CD8 T cells in spleen at day 7 after treatment." (PMID 32005809, 2020). "Confirming what was described in the previous experiments, analysis of T cell populations revealed increased expansion and persistence of adoptively transferred Thy1.1+ CD8 T cells in spleen and tumor of mice treated with ACT + NKTR-214 compared to ACT + IL-2, both at days 7 and 14 days." (PMID 32005809, 2020). "Thus, NKTR-214 shifted the balance between proliferation and apoptosis in the periphery versus in the tumor tissue, promoting expansion of intratumoral and peripheral CD8+ Teff while selectively depleting intratumoral but not peripheral Tregs." (PMID 32005826, 2020). "Within the inherent limitations of studying T-cell subset dynamics in tumor tissue from patients treated in a phase I clinical trial, these observations were not in contradiction with a mechanism of selective depletion of intratumoral Tregs by NKTR-214." (PMID 32005826, 2020). "Furthermore, in vivo depletion of CD8+ T cells in mice treated with vaccine and NKTR-214, completely abrogated intratumoral Treg depletion, demonstrating a direct contribution of tumor-specific, CD8+ Teff to intratumoral Treg depletion." (PMID 32005826, 2020). "When NKTR-262 is administered in combination with NKTR-214 the combined effect of innate immune stimulation and enhanced antigen presentation with sustained T cell activation leads to systemic tumor immunity." (PMID 30400835, 2018). "Using JAK1/2-KOs cell lines we showed that intratumoral administration of the TLR-9 agonist SD-101 was able to overcome local resistance to anti-PD-1 even in abscopal sites, and the NKTR-214 overcame resistance to anti-PD-1 in the B2M-KO tumor growth and significantly increased survival." (PMID 30400822, 2018).